ALX3 (ALX homeobox 3)
Description:
Transcriptional regulator with a possible role in patterning of mesoderm during development.
Synonyms: FND; FND1
Tractability: No criterion of Open Targets' tractability assessment is met for any kind of drug.
Gene: Protein-coding gene on chromosome 1 (110,059,870 to 110,070,672, reverse strand). Ensembl gene ENSG00000156150.
Subcellular location: Nucleus
Subcellular location (Human Protein Atlas): Nucleoli fibrillar center
Pathways (Reactome):
Developmental Biology: Transcriptional and post-translational regulation of MITF-M expression and activity
Gene Ontology:
Molecular function: sequence-specific double-stranded DNA binding; DNA-binding transcription factor activity, RNA polymerase II-specific; RNA polymerase II transcription regulatory region sequence-specific DNA binding; DNA binding
Biological process: neuron development; regulation of transcription by RNA polymerase II; regulation of DNA-templated transcription
Cellular component: chromatin; nucleus
Genetic constraint (gnomAD): Loss-of-function variants: 17 observed, 24.27 expected, observed/expected ratio (o/e) 0.7, 90% interval 0.48 to 1.05. The upper end of that interval is the gene's LOEUF score, 1.05, which puts it in group 4 of 6, group 1 being the genes least tolerant of losing a copy. Missense variants: 461 observed, 426.53 expected, observed/expected ratio (o/e) 1.08, 90% interval 1 to 1.17. Synonymous variants: 208 observed, 180.33 expected, observed/expected ratio (o/e) 1.15, 90% interval 1.03 to 1.29.
Gene-disease validity (ClinGen):
ClinGen rates the evidence that ALX3 causes each of these diseases.
frontorhiny (autosomal recessive): Definitive. Frontorhiny is a distinct syndromic type of frontonasal malformation characterized by hypertelorism, wide nasal bridge, broad columella, widened philtrum, widely separated narrow nares, poor development of nasal tip, midline notch of the upper alveolus, columella base swellings and a low hairline.
Homologues: Orthologues: chimpanzee ALX3 (99% identical), macaque ALX3 (96% identical), mouse Alx3 (92% identical), guinea pig ALX3 (91% identical), pig ALX3 (91% identical), rat Alx3 (90% identical), rabbit ALX3 (88% identical), dog ALX3 (85% identical). Paralogues in human: ALX4 (38% identical), ALX1 (37% identical), ARX (25% identical), RAX (24% identical), UNCX (24% identical), VSX2 (23% identical), PAX7 (22% identical), PAX3 (22% identical), PRRX1 (21% identical), OTP (21% identical), PHOX2B (21% identical), PITX2 (21% identical), and 38 more.
Diseases named in the same sentence as ALX3 in open-access papers:
ALX3 is named in the same sentence as 38 diseases in open-access papers, as found by Europe PMC text mining. Sharing a sentence is not in itself a finding about the gene and the disease. The quoted sentences say what the papers report.
frontonasal dysplasia (9 papers, 2012 to 2025). A group of rare bone development disorders characterized by an array of abnormalities affecting the eyes, forehead, and nose, and linked to midfacial dysraphia. "An illustrative example is the L168V mutation in the gene ALX3, which causes the rare disease frontonasal dysplasia." (PMID 37878721, 2023). "In humans, homozygous mutation of Alx3 has been associated with a form of frontonasal dysplasia known as frontorhiny." (PMID 37681295, 2023). "Alx3 has primarily been studied in the context of craniofacial skeletal development: homozygous recessive mutations in humans cause frontonasal dysplasia." (PMID 32857879, 2020). "Indeed, Alx3 deficiency in mice can lead to lethal neural tube closure defects, and in humans, mutations in the ALX3 gene are associated with inborn facial midline defects and frontonasal dysplasia." (PMID 39129011, 2024). "Mutations in genes encoding the ALX homeodomain-containing transcription factors (ALX1, ALX3 and ALX4) are associated with frontonasal dysplasia and produce midfacial phenotypes in vertebrate species." (PMID 38063857, 2024). "In humans, ALX1 mutations are linked to severe frontonasal dysplasia (FND) and extreme microphthalmia, and ALX3 and ALX4 genes are associated with a phenotypic spectrum of hypertelorism and nasal-tip duplications." (PMID 35142342, 2022). "However, it is important to bear in mind that ALX3-dependent frontonasal dysplasia is a rare disease with only a relatively small number of cases reported, and that patients are usually children within the first few years of life." (PMID 39129011, 2024). "Given the spectrum of human midfacial anomalies associated with disrupted functions of TFAP2A (branchio-oculo-facial syndrome), TFAP2B (Char syndrome), and ALX1, ALX3 and ALX4 (frontonasal dysplasia), these findings link features of previously disparate disorders into a shared genetic hierarchy." (PMID 38063857, 2024). "Frontonasal dysplasia resulted from ALX1, ALX3, ALX4 can also present bifid nose." (PMID 38097983, 2023).
neuroblastoma (4 papers, 2011 to 2023). Neuroblastoma (NB) is the most common solid, extracranial childhood tumor. "ALX3 is a homeobox transcription factor implicated in differentiation and development and is reported to be hypermethylated in advanced-stage neuroblastomas." (PMID 36147741, 2022). "The genes exhibiting methylation values above normal samples include the oncogene PHOX2B, the neuroblastoma associated gene ALX3, the commonly methylated PCDHα gene cluster, POU4F2, REXO1L1, BAPX1, and the potassium-channel KCNJ8." (PMID 22174824, 2011). "The methylation of ALX3 has been associated with neuroblastoma, colorectal carcinoma, and HCC." (PMID 37760434, 2023). "Moreover, high expression of ALX3 is associated with better survival in neuroblastoma patients further implicating the significance of this gene as a critical regulator in neuroblastoma differentiation." (PMID 36147741, 2022). "We also observe increased levels of methylation in other cancer related genes e.g. ALX3 and PHOX2B both implicated in neuroblastoma." (PMID 22174824, 2011).
frontonasal dysplasia 1 (3 papers, 2016 to 2023). "Mutations in ALX3 result in frontonasal dysplasia 1 in humans and nasal clefts in mice." (PMID 27560520, 2016). "RUNX2, ALX3 and RARA are also central in multiple sequences and related to diseases in both human and mouse: cleidocranial dysplasia, frontonasal dysplasia 1 and acute promyelocytic leukemia respectively." (PMID 29161290, 2017).
cleft palate (2 papers, 2009 to 2016). Cleft palate is a fissure type embryopathy that affects the soft and hard palate to varying degrees. "Among these genes, ablation or mutation of Alx3, Lhx8, Pax3, Pitx1, Shox2, and Zeb2 induces cleft palates in humans and/or mice." (PMID 27329940, 2016).
colorectal cancer (2 papers, 2021 to 2023). A primary or metastatic malignant neoplasm that affects the colon or rectum. "Altered methylation of ALX3 was also found to be linked to colorectal cancer development." (PMID 34266408, 2021).
Glucose intolerance (2 papers, 2017 to 2024). Glucose intolerance (GI) can be defined as dysglycemia that comprises both prediabetes and diabetes. "Using Alx3-deficient mice on a hybrid FVBxC57BL/6J background we found altered glucose homeostasis due to dysfunctional pancreatic islets resulting in mild hyperglycemia, glucose intolerance and impaired insulin secretion." (PMID 39129011, 2024). "When tests were carried out in pregnant females, we found that wild type animals had developed a degree of glucose intolerance similar to that found in Alx3-deficient females, consistent with the normal metabolic adaptations of maternal glucose homeostasis during pregnancy." (PMID 28341857, 2017). "Since Alx3-deficient mice fed with a SCD are known to exhibit hyperglycemia and glucose intolerance, we assessed whether disparities in adiposity relative to control animals differentially affect insulin sensitivity." (PMID 39129011, 2024). "Glucose tolerance tests demonstrated the presence of relatively mild glucose intolerance in Alx3-deficient non-pregnant females as compared with wild type non-pregnant controls." (PMID 28341857, 2017). "All these data indicate that Alx3-deficient non-pregnant females have mild glucose intolerance, but this is not aggravated during pregnancy, being similar to the glucose intolerance associated with pregnancy in wild type animals." (PMID 28341857, 2017). "In contrast, pregnancy did not aggravate further the glucose intolerance observed in Alx3-deficient females, which remained similar to the glucose intolerance observed in wild type pregnant females." (PMID 28341857, 2017). "Since non-pregnant Alx3-deficient females had only a mild hyperglycaemia, we sought to determine whether pregnancy in these animals was associated with increased basal blood glucose levels or severe glucose intolerance." (PMID 28341857, 2017).
hepatocellular carcinoma (2 papers, 2019 to 2021). A malignant tumor that arises from hepatocytes. "ALX3 was reported as a DEG with a high DNA methylation in hepatocellular carcinoma." (PMID 34266408, 2021). "Indeed, ALX3, GJD2, and SLC22A2, are linked to the IPA pathways 'liver carcinoma' and 'hepatobiliary system cancer'." (PMID 31695765, 2019).
hyperglycaemia (2 papers, 2017 to 2024). "This synergistic increase indicates that Alx3 deficiency renders the embryos more vulnerable to the teratogenic effects of hyperglycaemia." (PMID 28341857, 2017). "Since oxidative stress and lack of ALX3 favour excessive embryonic apoptosis, we investigated whether ALX3-deficiency further increases the risk of embryonic damage during gestational hyperglycaemia in mice." (PMID 28341857, 2017). "Thus, ALX3 deficiency provides a novel molecular mechanism for developmental defects arising from maternal hyperglycaemia." (PMID 28341857, 2017). "Glucose up-regulates the expression of Alx3, which in turn stimulates the expression of Foxo1 and the expression of genes encoding oxidative stress-scavenging enzymes as alfa defence mechanism against excess ROS generated by hyperglycaemia." (PMID 28341857, 2017). "Instead, these changes reflect a role for ALX3 as a protective genetic buffer to temper the effects of hyperglycaemia on gene expression levels during a critical period of development." (PMID 28341857, 2017). "Our work indicates that Alx3 confers protection against oxidative stress produced by glucose in embryonic cells, thus contributing to the prevention of the teratogenic effects of hyperglycaemia during diabetic pregnancy." (PMID 28341857, 2017). "Thus, Alx3 emerges as an important glucose sensor to protect the organism against the harmful effects of hyperglycaemia." (PMID 28341857, 2017).
cervical cancer (1 paper, 2021). A primary or metastatic malignant neoplasm involving the cervix. "Altered expression of CDC25A and ALX3 was introduced in vitro and in vivo to access their functions in cervical cancer development." (PMID 34266408, 2021). "This study suggested that the ALX3 increased CDC25A expression through KDM2B-mediated demethylation of H3K4me3, which induced proliferation and cell cycle progression of cervical cancer cells." (PMID 34266408, 2021). "Therefore, we planned to validate the possible links between ALX3 and CDC25A and their functions in cervical cancer." (PMID 34266408, 2021).
cervical squamous cell carcinoma (1 paper, 2023). A squamous cell carcinoma arising from the cervical epithelium. "ALX3 is a member of the homeobox family with oncogenic potential in cervical squamous cell carcinoma through the transactivation of CDC25A by recruiting lysine demethylase 2B." (PMID 37760434, 2023).
diabetes (1 paper, 2017). "Remarkably, the proportion of craniofacial malformations in Alx3+/− or Alx3−/− embryos from diabetic pregnancies was considerably higher than expected if the effects of diabetes and Alx3 deficiency were additive (superscripts d and e, respectively)." (PMID 28341857, 2017). "Thus, taken together in the context of the present study, loss of function mutations in Alx3 emerge as putative determinants for increased risk of congenital craniofacial malformations associated with diabetes during pregnancy." (PMID 28341857, 2017). "On the contrary, maternal diabetes increased the expression of Foxo1, but this response was significantly blunted in Alx3-null embryos." (PMID 28341857, 2017). "Interestingly, Gcn5 expression was not affected by Alx3 deficiency even in the presence of maternal diabetes." (PMID 28341857, 2017). "Thus, the significant increase in cranial malformations observed when Alx3 deficiency and diabetes are present together reflects the absence of a protective role for Alx3 against the teratogenic effects of glucose." (PMID 28341857, 2017). "When compared with non-diabetic pregnancies, maternal diabetes significantly increased the number of Alx3−/− embryos with severe craniofacial malformations (superscript c)." (PMID 28341857, 2017). "In the case of Alx3-null animals, the number of embryos in non-diabetic pregnancies was lower than in non-diabetic wild type pregnancies, but litter size was not reduced further as a consequence of diabetes." (PMID 28341857, 2017).
facial cleft (1 paper, 2022). A congenital abnormality consisting of an opening or gap in the face, which results from incomplete fusion of one or more of the embryonic facial prominences. "Since some studies believed that the occurrence of the facial cleft was related to some genes related to craniofacial malformation such as IRF6, ALX1, ALX3, and ADH1C." (PMID 36090555, 2022).
frontofacionasal dysplasia (1 paper, 2011). Fronto-facio-nasal dysostosis is characterized by multiple craniofacial anomalies (brachycephaly, blepharophimosis, ptosis, S-shaped palpebral fissures, coloboma, cleft lip and palate, deformed nostrils, encephalocele, hypertelorism, midface hypoplasia, malformed eyes, and absent inner eyelashes). "The clinical symptoms caused by the loss-of-function mutations of the ALX1 gene were related to the clinical spectrum of frontofacionasal dysplasia caused by the two other ALX genes, ALX3 and ALX4." (PMID 21595979, 2011).
Insulin resistance (1 paper, 2024). Increased resistance towards insulin, that is, diminished effectiveness of insulin in reducing blood glucose levels. "In parallel, insulin resistance, that was evident in HFD-fed wild type mice relative to SCD-fed controls, was less pronounced in HFD-fed Alx3-deficient mice, which were more sensitive to insulin than controls." (PMID 39129011, 2024).
liver cancer (1 paper, 2025). An epithelial or non-epithelial malignant neoplasm that arises from the liver. "Although no consistent patterns for the Δβ of ALX3, NPTX2, and TRIM58 were observed across the stages, these three genes were stably hypermethylated in nearly all stages, except for NPTX2 at the fourth stage in liver cancer." (PMID 39944136, 2025).
melanoma (1 paper, 2019). A malignant, usually aggressive tumor composed of atypical, neoplastic melanocytes. "Finally, ALX3 is involved in color differentiation in striped rodents, and proposed as a target melanoma gene fusion in humans." (PMID 31275359, 2019).
microphthalmia (1 paper, 2022). Congenital or developmental anomaly in which the eyeballs are abnormally small. "Disruption of ALX1 causes severe facial clefting and microphthalmia in FND3 patients, whereas loss of function mutations in ALX3 and ALX4 underlie the milder FND1 and FND2 syndromes, respectively." (PMID 35127681, 2022).
Prader-Willi syndrome (1 paper, 2024). "In this regard, some of the main features of the Alx3-deficient mice phenotype including increased adiposity, decreased lean mass and decreased food intake are similar to those observed in mice deficient for Magel2, a gene whose mutations are associated with Prader-Willi syndrome in humans." (PMID 39129011, 2024).
cancer (5 papers, 2006 to 2025). A tumor composed of atypical neoplastic, often pleomorphic cells that invade other tissues. "Prediction results of the constructed universal model for validating the five additional cancers by using the optimal biomarker combination (ALX3, NPTX2, and TRIM58)." (PMID 39944136, 2025). "Prediction results of independent prediction models for the five low-survival-rate cancers by using the optimal biomarker combination (ALX3, NPTX2, and TRIM58)." (PMID 39944136, 2025). "The best combination of common methylation biomarkers derived from the five initial cancer types were ALX3, NPTX2, and TRIM58." (PMID 39944136, 2025). "However, to the best of our knowledge, there is limited evidence concerning the role of ALX3, as a transcription factor, in human cancer progression." (PMID 34266408, 2021). "Both the mRNA and protein expression of ALX3 was found to be increased in the cancer cell lines." (PMID 34266408, 2021). "The Δβ values of ALX3, NPTX2, and TRIM58 for five low-survival-rate cancers by stage." (PMID 39944136, 2025). "The Δβ values of ALX3, NPTX2, and TRIM58 for five low-survival-rate cancers." (PMID 39944136, 2025).
tumor (2 papers, 2006 to 2020). "Some of PMDGs were confirmed as tumor-suppressive genes, such as VASH1, ALX3, and LDN3." (PMID 32701143, 2020).
ALX3 also shares sentences with these, for which no sentence is quoted: cleft lip (3 papers); breast carcinoma (2); acute promyelocytic leukemia (1); ankyloglossia (1); auriculocondylar syndrome (1); Branchio-oculo-facial syndrome (1); Char syndrome (1); clear renal cell carcinoma (1); cleidocranial dysplasia (1); endometrial cancer (1); glioma (1); head and neck squamous cell carcinoma (1); insulinoma (1); Intellectual disability (1); malignant lymphoma (1); pancreatic cancers (1); pancreatic neuroendocrine neoplasm (1); stomach cancers (1).